PEBP1 (phosphatidylethanolamine binding protein 1)
Diseases named in the same sentence as PEBP1 in open-access papers (continued):
Sharing a sentence is not in itself a finding about the gene and the disease.
ischemia (2 papers, 2019 to 2022). A hypoperfusion of the BLOOD through an organ or tissue caused by a PATHOLOGIC CONSTRICTION or obstruction of its BLOOD VESSELS, or an absence of BLOOD CIRCULATION. "Among differentially expressed proteins, we validated that PEBP1 was significantly decreased in the lumbar region 3 h after ischemia." (PMID 31683736, 2019). "In a previous study, we utilized a proteomic approach and found a significant reduction in phosphatidylethanolamine-binding protein 1 (PEBP1) protein level in the spinal cord at 3 h after ischemia." (PMID 31683736, 2019). "In addition, our colleagues observed that phosphorylated PEBP1 levels significantly increase in the hippocampal CA1 region 1–2 days after ischemia." (PMID 31683736, 2019). "However, our previous proteomic study demonstrated that PEBP1 expression was decreased in the spinal cord 3 h after ischemia, and we also observed PEP-1-PEBP1 protected pyramidal neurons from transient forebrain ischemia in gerbils." (PMID 31683736, 2019). "In the PEP-1 peptide-treated and control-PEBP1-trateed groups, MPO, TNF-α, and HMGB levels were significantly robustly increased in the spinal cord 72 h after ischemia compared to those in the control group." (PMID 31683736, 2019). "Acute side effects of control-PEBP1 or PEP-1-PEBP1 10 min before and after ischemia were monitored, but we did not observe any significant change in physiological parameters such as pH, pO2, pCO2, or glucose levels." (PMID 31683736, 2019). "Spinal cord ischemia significantly increased the TNF-α levels in the spinal cord compared to that in the control group and administering PEP-1-PEBP1, not control-PEBP1, mitigated the ischemia-induced elevation of TNF-α levels in the spinal cord after ischemia/reperfusion." (PMID 31683736, 2019).
kidney cancer (2 papers, 2023). Primary or metastatic malignant neoplasm involving the kidney. "In contrast, PEBP1 mRNA levels were significantly lower across all kidney cancer subtypes (KICH, KIRC, and KIRP), as well as in LIHC, HNSC, THCA, LUAD, and LUSC tumors." (PMID 37894300, 2023).
metastatic prostate carcinoma (2 papers, 2012 to 2018). A carcinoma that arises from the prostate gland and has spread to other anatomic sites. "The loss of the Raf kinase inhibitor protein (RKIP), also known as a phosphatidylethanolamine binding protein 1 (PEBP1), is connected to the development of metastatic prostate cancers as well as a few other types of aggressive cancers." (PMID 30115852, 2018). "Although a few of these potential interactions were reported previously, in this study, we further present several novel interactions that might explain the possible role of RKIP/PEBP1 in autophagy and EMT during the development of metastatic prostate cancer." (PMID 30115852, 2018).
oligodendroglioma (2 papers, 2012 to 2015). A well-differentiated (WHO grade II), diffusely infiltrating neuroglial tumor, typically located in the cerebral hemispheres. "NPM1, RKIP/PEBP1 and GRP78 expressions were significantly distinct in GBMs and oligodendrogliomas compared to AST II and NN (p < 0.0001, blocked t test), corroborating previous data of our group." (PMID 26108672, 2015).
pancreatic ductal adenocarcinoma (2 papers, 2013 to 2025). An infiltrating adenocarcinoma that arises from the epithelial cells of the pancreas. "Notably, our findings revealed a significant positive correlation of PEBP1/STK11 co-expression and OS in pancreatic ductal adenocarcinoma (PAAD) exclusively, suggesting a potentially distinct role of these genes in PAAD progression and survival probability." (PMID 40806276, 2025).
schizophrenia (2 papers, 2021 to 2023). A major psychotic disorder characterized by abnormalities in the perception or expression of reality. "A study with a rare CNVs analysis by WGS suggested that a de novo deletion that affects TAOK3 (and PEBP1) may contribute to schizophrenia and TAOK3 (but not PEBP1) was further confirmed in a GWAS analysis, suggesting LOF of monogenic TAOK3 may contribute to NDDs, at least in schizophrenia." (PMID 33867937, 2021).
Sepsis (2 papers, 2022 to 2024). Sepsis is defined as life-threatening organ dysfunction caused by a dysregulated host response to infection. "Furthermore, we used the survival data of sepsis patients in GSE65682 to perform the survival analysis according to the expression levels of PEBP1 and LPIN1." (PMID 35222395, 2022). "PEBP1 and LPIN1 were both intersected among GSE65682, LPS 2h, and LPS 9h datasets, which indicated that these two genes might have been involved in sepsis-induced ferroptosis." (PMID 35222395, 2022).
age (1 paper, 2025). A temporal measurement of the time period elapsed since an identifiable point in the life cycle of an organism. "Given the crucial role of the ISR in the hippocampus for memory formation, it will be important to determine whether PEBP1 plays a role in these processes and thus whether PEBP1 could be targeted therapeutically in any age-related cognitive or neurodegenerative disorders." (PMID 39878441, 2025).
autoimmune encephalitis (1 paper, 2019). Inflammation of the brain secondary to an immune response triggered by the body itself. "In the animal model of MS, MOG-induced experimental autoimmune encephalitis in Dark Agouti rats, PEBP1 was one of the down-regulated genes in the remitting stage of this disease model." (PMID 31141529, 2019).
cognitive decline (1 paper, 2024). "Second, we showed that especially higher baseline levels of SNAP-25, and in lesser extent of NfL, Ng, β-syn, proteins of the 14-3-3 family, GDI-1 and PEBP-1 were associated with faster cognitive decline and disease progression along the AD continuum." (PMID 39121126, 2024). "Higher baseline levels of most proteins (SNAP-25, NfL, Ng, β-syn, γ-syn, AP2-complex subunit β [AP2], GDI-1, PEBP-1, all 14-3-3 proteins and CPLX2) were also associated with faster cognitive decline (interaction protein*time p < 0.05)." (PMID 39121126, 2024).
diffuse large B-cell lymphoma (1 paper, 2025). "In general, at least one of the genes that encode immune stimulators exhibited a positive correlation with PEBP1/STK11 expression across all cancer types, with the exception of CHOL, ESCA, UCS, and diffuse large B-cell lymphoma (DLBC)." (PMID 40806276, 2025).
endocrine cancers (1 paper, 2025). "Further analysis of additional ECM molecules, including VTN, EMC1, THBS3, and CLEC3B revealed a positive correlation trend with PEBP1/STK11 co-expression in endocrine cancers, while correlations in other cancer types varied, suggesting a context-dependent relationship." (PMID 40806276, 2025). "Similarly, collagens and other ECM structural components displayed largely negative correlations with PEBP1/STK11 co-expression, with the most frequent exceptions found in endocrine cancers, particularly in THYM." (PMID 40806276, 2025).
fibrosarcoma (1 paper, 2022). A malignant mesenchymal fibroblastic neoplasm affecting the soft tissue and bone. "PEBP1, also named RKIP (Raf kinase inhibitory protein), is well characterized by disrupting rapidly accelerated fibrosarcoma (Raf) and mitogen-activated protein (MEK) interaction via exclusive and competitive binding to either of them, leading to inhibition of signal transmission from Raf to MEK." (PMID 35955931, 2022).
gram-negative bacterial infections (1 paper, 2018). Infections caused by bacteria that show up as pink (negative) when treated by the gram-staining method. "Pebp1 binds phosphatidylethanolamine, and overexpression of this gene is associated with protection against both gram-positive and gram-negative bacterial infection in the fly via release of various immunity-related proteins into their hemolymph." (PMID 29141990, 2018).
inflammatory bowel disease (1 paper, 2018). A spectrum of small and large bowel inflammatory diseases of unknown etiology. "The reduction in PEBP1/RKIP was also reported in aged neuron and skin, although increased PEBP1/RKIP expression in inflammatory bowel disease was recently reported." (PMID 29719584, 2018).
metabolic myopathies (1 paper, 2014). "VPA alters the expression of PEBP1, BHMT, MYL1, ALB and FLNC that are closely related with metabolic myopathies, myogenesis, albumin gene expression, and haemolytic anemia." (PMID 25551574, 2014).
pituitary tumor (1 paper, 2023). A benign or malignant neoplasm affecting the pituitary gland. "Moreover, drugs specifically designed to target KLK10 and PEBP1 would be welcome, and would be useful for pituitary tumors currently lacking an efficient medical treatment." (PMID 37033229, 2023).
psoriasis (1 paper, 2022). An autoimmune condition characterized by red, well-delineated plaques with silvery scales that are usually on the extensor surfaces and scalp. "Moreover, PEBP1 up-regulation was associated with various psoriasis pathogenesis-related pathways, like ‘NOD LIKE RECEPTOR SIGNALING PATHWAY’, ‘JAK‐STAT SIGNALLING PATHWAY’, ‘CYTOKINE CYTOKINE RECEPTOR INTERACTION’, and ‘TOLL LIKE RECEPTOR SIGNALING PATHWAY’." (PMID 36685512, 2022). "Among them, PEBP1, PRKAA2 and ACSF2 are associated with ferroptosis and participate in regulating immune microenvironment in psoriasis cases." (PMID 36685512, 2022). "Besides, based on CIBERSORT analysis, alterations of immune microenvironment in psoriasis cases were possibly associated with PRKAA2, PEBP1, CISD1, and ACSF2." (PMID 36685512, 2022). "Typically, ABCC5 (p = 0.0012), CISD1 (p= 3.9e−10) and TRIB2 (p < 2.22e−16) levels in psoriasis cases increased compared with healthy samples, whereas NR5A2 (p = 1.8e−13), PEBP1 (p < 2.22e−16) and PRKAA2 (p < 2.22e−16) levels decreased in psoriasis samples." (PMID 36685512, 2022). "For immune cells, T cells and Monocytes were related to PEBP1, MDM2, TIMM9 and DCAF7 in psoriasis group." (PMID 36685512, 2022). "Typically, CISD1 (p = 3.9e-10), TRIB2 (p < 2.22e−16), and ABCC5 (p=0.0012) levels among psoriasis cases increased compared with healthy controls, whereas PRKAA2 (p < 2.22e−16), ACSF2 (p = 3e−15), TIMM9 (p= 0.049), PEBP1 (p < 2.22e−16) and NR5A2 (p=1.8e−13) levels decreased among psoriasis cases." (PMID 36685512, 2022).
pulmonary diseases (1 paper, 2022). "This might be due to the fact that PEBP1 is more closely associated with pulmonary diseases." (PMID 35222395, 2022).
renal carcinoma (1 paper, 2025). A carcinoma arising from the epithelium of the renal parenchyma or the renal pelvis. "In renal cancer cells, increased expression of the E3 ligase UBE3C increased the expression level of Phosphatidylethanolamine Binding Protein 1 (PEBP1)." (PMID 40225869, 2025).
tumor (158 papers, 2007 to 2026). "Our next point of attention was to decipher associations between YY1/PEBP1 methylation (beta values) and immune cell infiltrates, across different tumor types." (PMID 37894300, 2023). "We thus explored the associations between YY1 (or PEBP1) expression and immune signatures, tumor immune cell infiltration, TMB, stemness, and microsatellite instability (MSI) in the TCGA database, using the R package “UCSCXenaShiny”." (PMID 37894300, 2023). "It is conceivable that PEBP1 variants could play a role in tumor growth by interfering with PEBP1 inhibitory functions in survival and anti-apoptotic signalling pathways." (PMID 18652693, 2008). "We conducted an in silico analysis using TCGA, which revealed a significant reduction in RKIP (PEBP1) expression in tumor tissues—LUAD and LUSC—compared to normal tissues." (PMID 40720248, 2025). "This indication suggests the potential role of PEBP1/STK11 co-expression in tumor suppression or altered metabolic regulation in hypoxic conditions." (PMID 40806276, 2025). "As we expected, RRM2, SLC2A1, DDIT4, and VDAC2 were significantly upregulated transcriptionally and translationally in tumor samples, whereas PEBP1 and IL33 are significantly reduced in tumorous tissues." (PMID 39311766, 2024). "scRNA-seq analysis showed that PEBP1 was highly expressed in various cells in the tumor microenvironment, including T cells, NK cells, Macrophage, Epithelial cells, B cells, Smooth muscle cells, Monocyte, and Endothelial cells." (PMID 37622116, 2023). "Downregulation of PEBP1 expression can promote tumor development and metastasis, while overexpression of PEBP1 can inhibit tumor metastasis and is of significant importance for patients’ prognosis and treatment." (PMID 37622116, 2023). "Overall, our findings underscore the significant role of the interplay between YY1 and PEBP1 in cancer progression, influencing genomic changes, tumor immunity, or the tumor microenvironment." (PMID 37894300, 2023). "CD79B was highly expressed in B cells, while PEBP1 was highly expressed in various types of cells in the tumor microenvironment." (PMID 37622116, 2023). "Aside from this, the analysis of the clinical sample and TCGA database indicated that a high PEBP1 expression correlated with a low PEBP1P2 expression in tumor tissues." (PMID 36348434, 2022). "The phosphatidylethanolamine-binding protein 1 (PEBP1) inhibits tumour metastasis initiation and acts as an endogenous tumour suppressor." (PMID 35203304, 2022). "A large part of the literature has focused on the role of PEBP1 as a tumor suppressor, and indeed, PEBP1 also plays a vital role in the pathology of AR." (PMID 35635016, 2022). "Bioinformatics analysis indicated that the protein level of PEBP1 was negatively correlated with tumor size, pathologic T stage and Fuhrman grade in the cRCC cohort from the CPTAC database." (PMID 35840930, 2022). "As an important ferroptosis regulator, PEBP1 mediates many tumor processes, including development, metastasis formation, and tumor microenvironment, for example through inflammation." (PMID 36348434, 2022). "In vivo experiments have also obtained consistent results that DHA can inhibit tumor growth and affect the expression of ferroptosis markers in tumor tissues, which would be partially offset by interference with PEBP1." (PMID 34925691, 2021). "As seen from the tumor representative map and tumor growth curve, interference with PEBP1 can significantly promote tumor growth." (PMID 34925691, 2021). "The upregulated ACSL3, DDIT4, RRM2, and SLC2A1 with HR > 1 were considered as oncogenes, whereas the downregulated HERPUD1 and PEBP1 with HR < 1 were regarded as tumor suppressors." (PMID 34499810, 2021). "It has been well established that PEBP1 suppresses the metastatic spread of tumor cells, and, moreover, the down-regulated expression of PEBP1 is observed in a number of human cancers." (PMID 23504277, 2013).
tumor (continued). "Importantly, PEBP1/STK11 co-expression was consistently linked to reduced expression of drug resistance genes and greater chemosensitivity across multiple tumor types." (PMID 40806276, 2025). "Raf kinase inhibitory protein (RKIP), encoded by the PEBP1 gene, a metastasis suppressor, modulates key oncogenic pathways and may influence tumor aggressiveness and therapy response." (PMID 40720248, 2025). "It is widely recognized that PEBP1 inhibits the metastatic dissemination of tumor cells." (PMID 37762371, 2023). "ST1926 treatment down-regulated a group of oncogenic proteins (SLC2A1, SLC25A6, CBX3, DEK, DDX39B) and up-regulated a group of presumably tumor-suppressing proteins (PEBP1, HspBP1); PADI2 and CMPK1, of unknown function in GBM, were also up-regulated." (PMID 37762371, 2023). "Recent studies have found that PEBP1 plays a vital role in tumor development." (PMID 35883650, 2022). "PEBP1 mediates ferroptosis and serves as a tumor-suppressor gene in various cancers." (PMID 36348434, 2022). "PEBP1 was found to be downregulated in several tumor cells and act as a metastasis suppressor." (PMID 36467089, 2022). "Although we discovered a similar favorable association between high PEBP1 expression and survival, our finding is on white blood cells, not on tumor cells." (PMID 28978044, 2017). "Here, further in-depth analysis of the genes that are co-expressed with PEBP1 suggests that its increased expression after vaccination is indicative of the beneficial skewing of the adaptive immune system towards an effective anti-tumor response." (PMID 28978044, 2017). "It remains to be determined whether PEBP1 is directly driving the skewing of T cell-mediated immunity towards robust anti-tumor responses, or is merely a bystander gene reflecting the state of the immune system." (PMID 28978044, 2017). "Overexpression of PEBP1-RKIP sensitizes tumor cells to chemotherapeutic drug-induced apoptosis." (PMID 18652693, 2008). "In addition, PEBP1 could be an informative biomarker of tumor regrowth, useful for predictive medicine in NF-PitNET." (PMID 37033229, 2023). "To discover the prognostic value of YY1 and PEBP1 in pan-cancer, we analyzed differences in patient survival between high and low expression groups of the two genes, and found that the expression of both genes significantly (p < 0.05) correlates with survival in different tumor types." (PMID 37894300, 2023). "Immunohistochemical database analysis reveals that EIF4EBP1, RIMKLA, and BIRC5 are highly expressed in tumour tissues, while the PCK1, PLG, PEBP1, and CAT show a lower expression in tumour samples." (PMID 40591061, 2025). "To further investigate the role of PEBP1 and STK11 co-expression within the tumor microenvironment (TME), we conducted a comprehensive set of analyses." (PMID 40806276, 2025). "Mechanistically, hsa-POLR2A_0005 forms a ternary complex with UBE3C and PEBP1, thereby enhancing PEBP1 ubiquitination and degradation, activating the ERK signaling pathway, and driving tumor progression." (PMID 41487511, 2025). "Overall, these findings suggested that RRM2, SLC2A1, DDIT4, and VDAC2 were potential oncogene, whereas PEBP1 and IL33 were candidate tumor suppressor genes." (PMID 39311766, 2024). "Of note, seventeen of thirty-nine proteins are reported as urine biomarkers in different diseases, of which eight proteins (PEBP1, EPS8L2, SERPINA1, FGA, SPINT1, CD55, SPARC, and GINM1) are related to neoplastic disease in urine specimens." (PMID 36918772, 2023). "Considering all the models, a patient stratification based on the extrasellar growth of the tumor, sex, age and the expression of E-cadherin, GHRL, IN1-GHRL, DRD2, SSTR5 and PEBP1 is proposed, with accuracies that stand between 71 to 95%." (PMID 35643771, 2022). "The proteomic clusters included tumor upregulated (PRDX3, APOA1, CLIC1) and downregulated (NFM, NDUS1, MDHC, ALDOC, STMN1, PEBP1, DDAH1, CN37) proteins." (PMID 25050814, 2014).